ENSG00000278276 (novel transcript)
Gene: Long non-coding RNA gene on chromosome 20 (31,573,007 to 31,581,214, forward strand). Ensembl gene ENSG00000278276.
Gene Ontology:
Molecular function: U4 snRNA binding
Biological process: formation of quadruple SL/U4/U5/U6 snRNP; spliceosomal tri-snRNP complex assembly
Cellular component: U4/U6 x U5 tri-snRNP complex; U6 snRNP